MYOG (myogenin)
Diseases named in the same sentence as MYOG in open-access papers (continued):
Sharing a sentence is not in itself a finding about the gene and the disease.
muscle atrophy (13 papers, 2011 to 2025). The loss of muscle tissue due to inactivity or disease. "Recently, myogenin was shown to transcriptionally activate the E3 ubiquitin ligases Fbxo32 and Trim63 following muscle denervation, and the loss of myogenin during adult life confers a resistance to denervation-induced muscle atrophy." (PMID 21264243, 2011). "Western blotting and RT-PCR were utilized to analyze MyoD, Myogenin, Atrogin-1, and MuRF1 protein and gene expression in a muscle atrophy model, as well as the Akt/mTOR and FoxO3α pathways." (PMID 39770504, 2024). "In a muscle atrophy model, the expression of Atrogin-1 and MuRF1 increased, and that of muscle differentiation factors, such as myogenin and MyoD1, decreased." (PMID 35736168, 2022). "Therefore, we suggest that curcumin may reduce the expression of muscle degrading factor myostatin and increase the myogenic factor myogenin to achieve the effect of reducing cachexia-related muscle atrophy." (PMID 35132306, 2022). "Muscle atrophy in POUND mice is associated with a marked decrease in muscle fiber diameter, and not surprisingly primary myoblasts from POUND mice fail to differentiate normally and show reduced expression of the myogenic factors MyoD and myogenin compared to myoblasts from normal mice." (PMID 23967295, 2013). "In different models of muscle atrophy such as spinal cord atrophy, amyotrophic lateral sclerosis, and Huntington disease, upregulation of the HDAC-4-myogenin axis has been reported, highlighting the central role of this axis on muscle degeneration." (PMID 33375628, 2020). "Muscle atrophy was triggered by the PBM-based diet, but this effect was improved with FPHs supplementation, as demonstrated by a significant increase in muscle fiber quantification (fiber density, hyperplasia, and hypertrophy) and muscle health relevant gene expression (IGF-1, myf5, and MyoG)." (PMID 37057066, 2023).
leiomyosarcoma (12 papers, 2010 to 2025). An uncommon, aggressive malignant smooth muscle neoplasm, usually occurring in post-menopausal women. "The morphological findings of the present case indicated a myxoid type of leiomyosarcoma, but immunohistochemistry revealed that a few tumor cells showed positive reactivity for myogenin." (PMID 21329505, 2011). "SCRMS may resemble fibrosarcoma or leiomyosarcoma, making desmin and myogenin and myoD1 stains important parts of the workup of infantile fibrosarcomatous lesions." (PMID 30613391, 2018). "In contrast to ERMS, leiomyosarcomas stain negatively for myoglobin and myogenin." (PMID 27357857, 2016). "Immunohistochemical staining shows an expression of SMA, muscle-specific actin, and desmin in most leiomyosarcomas, and expression of S-100 protein, CD34, Ki-67, myogenin, and cytokeratin has also been reported in some cases." (PMID 34544483, 2021). "Finally, the possibility of transdifferentiation or synchronous smooth and skeletal muscle differentiation in leiomyosarcoma was suggested in the present case because synchronous expression of α-SMA and myogenin was confirmed in 1.0% of spindle cells." (PMID 21329505, 2011). "Additionally, leiomyosarcoma shows reactivity to Desmin, Actin and Myogenin, but vascular markers are not expressed." (PMID 31311568, 2019). "Leiomyosarcoma with an epithelioid morphology show necrosis, atypical mitosis, and epithelioid cell morphology, and stain on immunohistochemistry for SMA and Myogenin which are negative in granular cell tumours." (PMID 34514564, 2022).
sarcoma (12 papers, 2010 to 2025). A usually aggressive malignant neoplasm of the soft tissue or bone. "We think that the reason for that is limited tissue material and that the myogenin staining was present only focally in a few sarcoma cells." (PMID 36292216, 2022). "The absence of lineage-specific markers, including EMA, CD34, CD31, myogenic markers (MyoD1, myogenin), melanocytic markers (HMB-45), and lymphoid markers (CD45), helped exclude alternative diagnoses such as sarcomas and hematologic malignancies." (PMID 41552210, 2025). "Eighty-six poorly-differentiated neoplasms were categorized as carcinomas, sarcomas, lymphomas or neuroendocrine cancers with a panel of 7 antibodies (cytokeratin AE1/AE3, vimentin, desmin, myogenin, leukocyte common antigen and neuron-specific enolase)." (PMID 21044352, 2010). "In line with the histological findings, propagated tumor cell cultures also revealed co-existence of different cell types, most prominently myogenin-positive cells and lipogenic but myogenin-negative cells, providing further support that tumors arising in MD-mice are mixed-type sarcomas." (PMID 21533183, 2011). "Importantly, MYOG and CHRNG were overexpressed in this cluster, indicating that referencing gene expression profiles may assist with the categorization and diagnosis of pediatric sarcomas." (PMID 34131151, 2021). "As expected, the Rabdhomyosarcoma markers Myogenin and Myoglobin were not expressed, further demonstrating the ability of the LMS undifferenitated cells to differentiate in vivo into a sarcoma of the same subtype as the patient tumor." (PMID 23056514, 2012).
lymphoma (10 papers, 2010 to 2025). A malignant (clonal) proliferation of B- lymphocytes or T- lymphocytes which involves the lymph nodes, bone marrow and/or extranodal sites. "For example, lymphoma may cause a large mediastinal mass with associated systemic symptoms but would differ in immunophenotype from ERMS and lack specific myogenin expression." (PMID 39703342, 2024).
neuroblastoma (8 papers, 2014 to 2025). Neuroblastoma (NB) is the most common solid, extracranial childhood tumor. "DEHP suppressed the calcium signaling of human nicotinic acetylcholine receptors in human neuroblastoma and induced a decrease in myotube formation in C2C12 cells, associated with reduced MyHC, MyoD and myogenin levels." (PMID 28085963, 2017). "The RMS component was strongly positive for myogenin and desmin by immunohistochemical staining, while the neuroblastoma component was stained with neural markers such as PGP9.5 and tyrosine-hydroxylase, CD56, synaptophysin, and S100." (PMID 25405050, 2014).
embryonal rhabdomyosarcoma (7 papers, 2016 to 2026). A poorly circumscribed morphologic variant of rhabdomyosarcoma. "Patient 47 was initially diagnosed with an embryonal rhabdomyosarcoma but was found in our current analyses to be immunonegative for all of the tested muscle markers including desmin, myogenin, myoglobin, and myoD1." (PMID 37395142, 2023). "The authors found cytoplasmic positivity for desmin and nuclei positivity for myogenin, in embryonal rhabdomyosarcoma, and also in one case positivity for MyoD1 (Peters S., Silva J., Morales L., Beghdad M., Bhandarkar A.,and Shahidatul-Adha M.)." (PMID 36173721, 2022). "The final diagnose was embryonal rhabdomyosarcoma (ERMS) with immunohistochemical staining positivity for myogenin, smooth muscle actin (EMA), desmin and myoD1." (PMID 32736545, 2020). "Immunohistochemical stains were positive for vimentin, CD99, myogenin, and MyoD1 consistent with a diagnosis of embryonal rhabdomyosarcoma, botryoid subtype." (PMID 29375950, 2017). "Myogenic markers (desmin, myogenin, MyoD1) are negative, excluding the differential diagnostic consideration of embryonal rhabdomyosarcoma, which frequently also has myxoid stroma, and shows locally aggressive features on imaging." (PMID 39597961, 2024). "Cytoplasmic positive for desmin and nuclei positive for myogenin in embryonal rhabdomyosarcoma." (PMID 36173721, 2022). "An ultrasound-guided biopsy showed embryonal rhabdomyosarcoma on histology and immunohistochemistry, with strong positivity of neural cell adhesion molecule and myogenin while results for cytokeratin AE1/AE3, cluster of differentiation 45, synaptophysin, and chromogranin were negative." (PMID 27998313, 2016). "The tumour cells were strongly and diffusely positive for Myogenin, which aids in distinguishing ARMS from embryonal rhabdomyosarcoma." (PMID 41556058, 2026).
rhabdomyoma (7 papers, 2023 to 2026). A benign mesenchymal tumor arising from skeletal or cardiac muscle. "Repeated vobra duo doses ameliorated this outcome, reverting rhabdomyosarcorma to rhabdomyoma tumor, by increasing Desmin and Myogenin/Myf-4 differentiation markers expression, and reducing both Ki-67 and CD133." (PMID 41507126, 2026). "Immunohistochemical staining was positive for MSA, Desmin, MYOD1 and Myogenin, leading to a final pathological diagnosis of adult rhabdomyoma." (PMID 39963349, 2025). "Immunoperoxidase staining can also help identify rhabdomyoma histology, with neoplastic muscle tissue staining positively for myoglobin and myogenin, and negatively for S100." (PMID 38963610, 2024). "Myogenin stains positively in fetal striated muscle and would be present in both the rhabdomyoma and surrounding normal cardiac tissue." (PMID 38963610, 2024).
Obesity (6 papers, 2017 to 2023). Accumulation of substantial excess body fat. "Specifically, HFD-induced obesity was associated with inhibition of the MyoD/Myogenin pathway in mice skeletal muscle." (PMID 32041272, 2020). "It was interesting that Gatm (L-arginine: glycine amidinotransferase), which is known to be related to obesity associated with creatine metabolism, showed the highest expression after myogenin." (PMID 30671462, 2018). "This impairment in SC fusion may be a result of decreased expression of MyoD, myogenin, and myosin heavy chain or could be linked to chronic inflammation associated with obesity." (PMID 32776502, 2020). "At 7 dpi, obesity attenuated mRNA expression of muscle regenerating markers, MyoD, and tended to decrease Pax7 and Myogenin expression." (PMID 36513394, 2023).
sarcomatoid carcinoma (6 papers, 2011 to 2024). A malignant epithelial neoplasm characterized by the presence of spindle cells and anaplastic morphologic features. "For example, in the case of sarcomatoid carcinomas, mesenchymal markers such as S100, myogenin, and MYOD1 are used for staining, which varies according to the specific subtype." (PMID 39001412, 2024). "Desmin and myogenin immunoreactivity can be used to differentiate RMS from other round cell tumors without rhabdomyoblastic differentiation but not sarcomatoid carcinoma with rhabdomyoblastic differentiation." (PMID 30390704, 2018). "As other immunohistochemical markers were negative, including CD45, CD163, CD68, Desmin, Myogenin, Melanoma, S100, α-SMA, Cytokeratin 7, Cytokeratin 20, MDM2 and CDK4, the tumors were diagnosed as sarcomatoid carcinomas." (PMID 29874846, 2018).
Cachexia (4 papers, 2020 to 2022). Severe weight loss, wasting of muscle, loss of appetite, and general debility related to a chronic disease. "We also measured the levels of PAX7, a transcription factor whose expression is sustained by NF-κB during C26-mediated cachexia, and those of myogenin, because the latter is known to induce atrogin-1." (PMID 32824440, 2020). "Furthermore, the number of myocytes (MyoD+/myogenin+ cells) was also reduced in the gastrocnemius of mice exposed to either unloading or cachexia conditions and in animals bearing the two conditions simultaneously." (PMID 33142912, 2020). "Muscle regeneration is highly compromised in cachexia conditions, and proliferating Pax7+ve cells are unable to terminally differentiate (and to express myogenin) and fuse into myofibers because they are prevented by tumour‐derived factors influencing the muscle microenvironment." (PMID 32159297, 2020). "We exclude that myogenin+ve nuclei observed in myofibers of cachectic mice derive from muscle precursor cells because in cachexia conditions activated muscle precursor cells are unable to terminally differentiate (and to express myogenin) and fuse into myofibers." (PMID 32159297, 2020). "Compared to NI-control animals, in muscles of the two unloaded groups of animals and in the two LC-cachexia mice, myoblast (Pax-7+ and MyoD+) counts did not significantly differ, whereas the numbers of myocytes (MyoD+ and myogenin+) significantly decreased." (PMID 33142912, 2020). "Strikingly, PM01183 efficiently reduced PAX7 and myogenin levels, but it is unlikely that such drug completely resolves the myogenic impairment typical of cachexia, as suggested by the failure of PM to restore C/EBPβ to normal levels." (PMID 32824440, 2020). "Collectively, these results suggested that overexpression and hyper‐stimulation of RAGE induced by high S100B might trigger muscle atrophy via a p38 MAPK/myogenin axis and STAT3‐dependent MyoD degradation, possibly amplifying the activity of cachexia‐inducing cytokines." (PMID 32159297, 2020).
fibrosarcoma (4 papers, 2018 to 2025). A malignant mesenchymal fibroblastic neoplasm affecting the soft tissue and bone. "Histopathology showed low-grade fibrosarcoma; immunohistochemistry was positive for Vimentin and SMA, focally CD34, and negative for S100, Desmin, and Myogenin, with low Ki-67 (<3 %)." (PMID 41045685, 2025). "These infantile fibrosarcomas were diffusely and robustly positive for Trk (100%), S100 protein (50%, 3/6 cases), nestin, CD10 (80%, 4/5 cases), and vimentin (100%), but negative for CD34, SMA, desmin, myogenin, and CD56." (PMID 32957984, 2020).
muscular atrophy (4 papers, 2020 to 2023). "Cisplatin-induced skeletal muscle atrophy is believed to be associated with not only the activation of muscle-specific ubiquitin ligases, but also reduced levels of IGF1, MyoD1, and myogenin." (PMID 37298128, 2023). "Studies have shown that MYOG expression is only upregulated in neurogenic muscular atrophy, but not significantly increased in muscular atrophy caused by fasting or cancer cachexia." (PMID 34276308, 2021). "In C2C12 myoblasts, miR-186 inhibits the muscle cell differentiation through myogenin regulation, while the expression level of miR-186 was decreased in the in the vivo starvation induced muscular atrophy mouse model, which suggests that miR-186 could alleviate muscular atrophy." (PMID 37894995, 2023).
Sepsis (4 papers, 2015 to 2023). Sepsis is defined as life-threatening organ dysfunction caused by a dysregulated host response to infection. "In conclusion, the lower activation of both glucocorticoid signaling and HDAC4-myogenin pathways by sepsis can be one of the causes of lower sepsis-induced proteolysis in the diaphragm compared to gastrocnemius." (PMID 35408999, 2022). "In skeletal muscle, our results show that pretreatment with the nutraceutical ameliorates the stimulatory effect of sepsis on the gene expression of the proteolytic markers atrogin-1 and MuRF1, as well as on the mRNA levels of LC3b, myogenin and HDAC4." (PMID 35795581, 2022). "The inhibition of TGF‐β/TβRII‐Akt‐Myogenin signalling by SPSB1 may shed light on the pathogenesis of the perturbed regenerative capacity observed in muscle of critically ill patients with sepsis." (PMID 37209006, 2023). "In addition to atrogin-1 and MuRF1 overexpression, an increase in muscle HDAC4 and myogenin has been recently reported in sepsis, and in other conditions that induce muscle atrophy such as neurological disease, disuse and aging." (PMID 35795581, 2022). "Sepsis also increase HDAC4 (p < 0.05) and myogenin (p < 0.01) protein levels in gastrocnemius muscle and nutraceutical pretreatment prevented this increase." (PMID 35795581, 2022). "In vivo, 8-fold and 49-fold fewer SCs expressed MyoG in septic mice 4 days and 7 days, respectively, post injury and sepsis compared with non-septic injured mice." (PMID 26666572, 2015).
Arthritis (3 papers, 2012 to 2023). Inflammation of a joint. "In addition, fenofibrate reverts arthritis-induced decrease in soleus mass and this effect is associated with decreased expression of Murf1 and myostatin, as well as upregulation of MyoD and myogenin expressions." (PMID 23781298, 2012). "Arthritic rats had higher soleus MyoD mRNA and protein in comparison with pair-fed and control rats (P<0.05), whereas myogenin expression was not modified by arthritis." (PMID 23781298, 2012).
carcinosarcoma (3 papers, 2020 to 2025). A malignant tumor composed of a mixture of carcinomatous and sarcomatous elements. "MYOG, which encodes myogenin, was only upregulated in carcinosarcoma tumours." (PMID 32899298, 2020). "The two carcinosarcomas showing heterologous skeletal muscle differentiation showed focal desmin and myogenin expression." (PMID 41202566, 2025).
diabetes (3 papers, 2020 to 2026). "Here, we report that FMOD and MYOG expressions were higher in the muscles of 16-week-old than in those of 2-year-old mice; however, expressions of muscle aging, diabetes, and intracellular lipid accumulation-related genes were higher in aged mice (2-year-old) muscles." (PMID 34440852, 2021).
Duchenne muscular dystrophy (3 papers, 2010 to 2023). Duchenne muscular dystrophy (DMD) is a neuromuscular disease characterized by rapidly progressive muscle weakness and wasting due to degeneration of skeletal, smooth and cardiac muscle. "Interestingly, it has been revealed that overexpression of Pax7 regulates myogenic differentiation by downregulating MyoD expression and prevents MyoG induction in fetal Duchenne Muscular Dystrophy (DMD) muscle tissues, suggesting a delay in myofibers differentiation program." (PMID 37685856, 2023).
small cell carcinoma (3 papers, 2011 to 2025). A neuroendocrine carcinoma composed of small malignant cells which are often said to resemble "oat cells" under the microscope. "In contrast, small cell carcinoma components, whether it is pure or admixed with urothelial carcinoma, were positive for cytokeratin and largely positive for chromogranin, and negative for myogenin." (PMID 21762516, 2011).
spindle cell sarcoma (3 papers, 2017 to 2021). A malignant mesenchymal neoplasm composed of spindle-shaped cells. "Resection specimen of the same case showed spindle cell sarcoma in a herring bone pattern, which on immunohistochemistry was negative for all specific lineage markers like smooth muscle actin, desmin, myogenin, pancytokeratin etc." (PMID 29204102, 2017).
adolescent idiopathic scoliosis (2 papers, 2022 to 2023). A scoliosis with no known cause arising in adolescent. "TENT5A also impacts the formation of muscle fibers in adolescent idiopathic scoliosis by preserving production of myogenin." (PMID 37239396, 2023).
breast carcinoma (2 papers, 2013 to 2024). "Accordingly, inhibition of the MAPK pathway leading to inactivation of myogenin or Myc could lead to down-regulation of ATAD3B and thus provide a putative therapeutic target for post-menopausal ER+/HER2− breast cancer patients." (PMID 23818839, 2013).
dermatomyositis (2 papers, 2023 to 2024). Dermatomyositis (DM) is a type of idiopathic inflammatory myopathy characterized by evocative skin lesions and symmetrical proximal muscle weakness. "A study comparing the expression of MRFs from muscle biopsies of patients with polymyositis, dermatomyositis, and sIBM showed that there is an increase expression of Pax7, MyoD, Myogenin, and neonatal myosin heavy chain compared with healthy controls." (PMID 36538023, 2023). "Analysis of muscle biopsies from dermatomyositis patients showed that in the advanced stage of perifascicular atrophy there is a perturbation of MRFs expression, characterized by an increase in Pax7 and Myogenin, but not MyoD." (PMID 36538023, 2023).
embryonal carcinoma (2 papers, 2015). A non-seminomatous malignant germ cell tumor characterized by the presence of large germ cells with abundant cytoplasm resembling epithelial cells, geographic necrosis, high mitotic activity, and pseudoglandular and pseudopapillary structures formation. "Wnt3a contributes to the post-translational regulation and activation of MyoD and MyoG during myogenesis in P19 embryonal carcinoma stem cells." (PMID 26247931, 2015).